ADAMTS13 (ADAM metallopeptidase with thrombospondin type 1 motif 13)
Description:
Cleaves the vWF multimers in plasma into smaller forms thereby controlling vWF-mediated platelet thrombus formation.
Synonyms: ADAM-TS13; ADAMTS-13; vWF-CP; C9orf8; VWFCP; TTP; FLJ42993; MGC118899; MGC118900; DKFZp434C2322
Tractability: Small molecule: it has a binding pocket of medium quality. Antibody: UniProt places it where antibodies can reach, with high confidence; its Gene Ontology location is reachable by antibodies, with high confidence; UniProt predicts a signal peptide or a membrane-spanning region.
Target class: Metallo protease MAM clan; Metallo protease; Protease; Enzyme; Metallo protease M12B subfamily
Gene: Protein-coding gene on chromosome 9 (133,414,358 to 133,459,402, forward strand). Ensembl gene ENSG00000160323.
Subcellular location: Secreted
Subcellular location (Human Protein Atlas): Vesicles; Predicted to be secreted
Pathways (Reactome):
Disease: Defective B3GALTL causes PpS; Defective VWF cleavage by ADAMTS13 variant; Enhanced cleavage of VWF variant by ADAMTS13
Hemostasis: Platelet Adhesion to exposed collagen; Regulation of clotting cascade
Metabolism of proteins: O-glycosylation of TSR domain-containing proteins
Gene Ontology:
Molecular function: metalloendopeptidase activity; protein binding; calcium ion binding; integrin binding; metallopeptidase activity; zinc ion binding; endopeptidase activity; peptidase activity
Biological process: peptide catabolic process; proteolysis; blood coagulation; cell-matrix adhesion; extracellular matrix organization; glycoprotein metabolic process; integrin-mediated signaling pathway; platelet activation; protein processing; cellular response to interleukin-4; cellular response to lipopolysaccharide; cellular response to tumor necrosis factor; cellular response to type II interferon; neutrophil extracellular trap formation; protein catabolic process; response to amine; response to interleukin-4; response to potassium ion; response to toxic substance; response to tumor necrosis factor; response to type II interferon
Cellular component: cell surface; endoplasmic reticulum lumen; extracellular matrix; extracellular region
Genetic constraint (gnomAD): Loss-of-function variants: 112 observed, 142.96 expected, observed/expected ratio (o/e) 0.78, 90% interval 0.67 to 0.92. The upper end of that interval is the gene's LOEUF score, 0.92, which puts it in group 3 of 6, group 1 being the genes least tolerant of losing a copy. Missense variants: 1,703 observed, 1,811.1 expected, observed/expected ratio (o/e) 0.94, 90% interval 0.9 to 0.98. Synonymous variants: 757 observed, 727.63 expected, observed/expected ratio (o/e) 1.04, 90% interval 0.98 to 1.11.
Gene-disease validity (ClinGen):
ClinGen rates the evidence that ADAMTS13 causes each of these diseases.
congenital thrombotic thrombocytopenic purpura (autosomal recessive): Definitive. Congenital thrombotic thrombocytopenic purpura is the hereditary form of thrombotic thrombocytopenic purpura (TTP) characterized by profound peripheral thrombocytopenia, microangiopathic hemolytic anemia (MAHA) and single or multiple organ failure of variable severity.
Homologues: Orthologues: chimpanzee ADAMTS13 (99% identical), macaque ADAMTS13 (95% identical), pig ADAMTS13 (76% identical), dog ADAMTS13 (71% identical), mouse Adamts13 (71% identical), rat Adamts13 (70% identical), guinea pig ADAMTS13 (66% identical), tropical clawed frog adamts13 (49% identical), zebrafish adamts13 (41% identical). Paralogues in human: ADAMTS7 (24% identical), ADAMTS12 (24% identical), ADAMTS9 (23% identical), ADAMTS20 (23% identical), ADAMTS18 (21% identical), ADAMTS16 (21% identical), ADAMTS17 (20% identical), ADAMTS10 (20% identical), ADAMTS6 (20% identical), ADAMTS2 (19% identical), ADAMTS3 (19% identical), ADAMTS14 (19% identical), and 13 more.
Diseases named in the same sentence as ADAMTS13 in open-access papers:
ADAMTS13 is named in the same sentence as 300 diseases in open-access papers, as found by Europe PMC text mining. Sharing a sentence is not in itself a finding about the gene and the disease. The quoted sentences say what the papers report.
thrombotic thrombocytopenic purpura (423 papers, 2005 to 2026). "It is a congenital form of thrombotic thrombocytopenic purpura (TTP) caused by ADAMTS13 protease deficiency because of mutations in the ADAMTS13 gene." (PMID 42196618, 2026). "A severe deficiency of ADAMTS13, a metalloprotease that cleaves ultra-large von Willebrand factor (vWF) multimers, causes thrombotic thrombocytopenic purpura (TTP) that is a subtype of primary TMA." (PMID 40990987, 2025). "Severe ADAMTS13 deficiencies are linked to thrombotic thrombocytopenic purpura, characterized by platelet-rich thrombi in the microvasculature." (PMID 39851513, 2025). "Thrombotic Thrombocytopenic Purpura (TTP) is an extremely rare microangiopathic hemolytic anemia characterized by a deficiency of ADAMTS-13, a von Willebrand Factor (vWF) cleaving protease." (PMID 39978057, 2025). "Thrombotic thrombocytopenic purpura (TTP) is a thrombotic microangiopathy associated with severe deficiency in ADAMTS13." (PMID 39883995, 2025). "Congenital thrombotic thrombocytopenic purpura (cTTP) related to ADAMTS-13 deficiency is associated with a maternal risk of death of 10% and a risk of fetal loss greater than 50% without treatment." (PMID 39995752, 2025). "Thrombotic thrombocytopenic purpura mainly arises from a deficiency or inhibition of ADAMTS13—a metalloproteinase responsible for cleaving a significant portion of von Willebrand factor (vWF)." (PMID 40933296, 2025). "Thrombotic thrombocytopenic purpura is a life-threatening illness caused by an abnormality in ADAMTS13 enzyme activity, leading to irregular blood clotting and organ damage." (PMID 40757115, 2025). "Thrombotic thrombocytopenic purpura (TTP) is a microangiopathic hemolytic anemia associated with ADAMTS-13 deficiency, a cleaving protease of von Willebrand factor (vWF)." (PMID 39978057, 2025). "Thrombotic thrombocytopenic purpura (TTP) is a life-threatening syndrome caused by a congenital or acquired reduction in the activity of the enzyme ADAMTS-13, which is involved in the cleavage of von Willebrand factor." (PMID 39941509, 2025). "Abnormal persistence of ultra-large VWF (ULVWF) multimers is caused by severe ADAMTS13 deficiency, which triggers thrombotic thrombocytopenic purpura (TTP), thereby predisposing microvascular thrombosis." (PMID 40362344, 2025). "Thrombotic thrombocytopenic purpura is caused by severe deficiency of ADAMTS13 due to acquired autoantibodies or genetic mutations." (PMID 40362344, 2025). "Current evidence indicates that vitamin B12 deficiency often co-exists with thrombotic thrombocytopenic purpura, a lethal micro-thrombotic disorder caused by severe ADAMTS13 deficiency and abnormal VWF accumulation." (PMID 40625905, 2025). "Deficiency of ADAMTS-13 has been related to thrombotic thrombocytopenic purpura and to an increased proportion of thrombotic events when Von Willebrand factors or D-Dimer are increased." (PMID 38892211, 2024). "Severe deficiency of ADAMTS13 (<10 iu/dL) is diagnostic of thrombotic thrombocytopenic purpura (TTP) and leads to accumulation of ultra-large vWF multimers, platelet aggregation, and widespread microthrombi, which can be life-threatening." (PMID 39274365, 2024). "Since larger VWF multimers possess higher platelet aggregation capacity, insufficient cleavage of UL-VWF multimers due to a deficiency in ADAMTS13 activity results in lethal thrombosis in patients with thrombotic thrombocytopenic purpura (TTP)." (PMID 39247211, 2024). "ADAMTS13 is associated with thrombotic thrombocytopenic purpura, ADAMTS5 with osteoarthritis, and ADAMTS7 is associated with atherosclerosis and coronary artery disease." (PMID 39329961, 2024). "Thrombotic thrombocytopenic purpura (TTP) is a rare thrombotic microangiopathy caused by a deficiency in the activity of ADAMTS13, a von Willebrand factor-cleaving protease." (PMID 38728448, 2024).
thrombotic thrombocytopenic purpura (continued). "TTP, or thrombotic thrombocytopenic purpura, is a life-threatening disorder caused by a deficiency of ADAMTS-13 (a disintegrin and metalloproteinase with a thrombospondin type 1 motif, member 13) activity." (PMID 39594185, 2024). "Compound heterozygous or homozygous mutations in the ADAMTS13 gene are associated with hereditary thrombotic thrombocytopenic purpura (TTP, also known as Upshaw–Schulman syndrome)." (PMID 37175682, 2023). "Thrombotic thrombocytopenic purpura is a life-threatening blood disorder caused by a marked deficiency in ADAMTS13 activity resulting in thrombocytopenia, microangiopathic hemolytic anemia, and multi-organ dysfunction." (PMID 38138254, 2023). "Thrombotic thrombocytopenic purpura is broadly defined as thrombotic microangiopathy occurring in the context of severe ADAMTS13 deficiency (< 10%)." (PMID 35949449, 2022). "The largest multimers are released from activated platelets, and in case the size regulating ADAMTS13 enzyme is deficient, such as occurs in thrombotic thrombocytopenic purpura (TTP)." (PMID 35433860, 2022). "Thrombotic thrombocytopenic purpura (TTP) results from a severe deficiency of the specific von Willebrand factor (VWF)-cleaving protease named ADAMTS13 (a disintegrin and metalloprotease with thrombospondin type 1 repeats, member 13)." (PMID 35163523, 2022). "Thrombotic thrombocytopenic purpura (TTP) is caused by ADAMTS13 deficiency leading to ultra-large vWF multimers." (PMID 36741833, 2022). "Thrombotic thrombocytopenic purpura (TTP) is a rare systemic form of TMA due to a severe deficiency in ADAMTS13." (PMID 36074708, 2022). "Thrombotic thrombocytopenic purpura (TTP) is a type of TMA defined by a deficiency of the metalloproteinase ADAMTS13, and can be immune-mediated (iTTP) or congenital (cTPP)." (PMID 36431152, 2022). "ADAMTS-13 deficiency results in vWF multimers built up and subsequent microvascular thrombosis and thrombocytopenia, a condition also known as thrombotic thrombocytopenic purpura (TTP)." (PMID 36295093, 2022). "Low levels of ADAMTS13 have also been described in thrombotic thrombocytopenic purpura and syndromes of thrombotic microangiopathy caused by infection." (PMID 35864532, 2022). "Severely reduced activity of ADAMTS-13 is the hallmark in the pathogenesis of thrombotic thrombocytopenic purpura (TTP)." (PMID 36703637, 2022). "The deficiency of ADAMTS13 causes a lethal thrombotic microvascular disease, thrombotic thrombocytopenic purpura (TTP)." (PMID 34946607, 2021). "Thrombotic thrombocytopenic purpura (TTP) is a rare thrombotic microangiopathy caused by decreased activity of ADAMTS-13 (A Disintegrin And Metalloproteinase with a ThromboSpondin type 1 motif, member 13), which leads to disseminated thrombus formation." (PMID 34895163, 2021). "Thrombotic thrombocytopenic purpura (TPP) is a rare blood disorder caused by an acquired or congenital deficiency in ADAMTS13 activity which results in clotting in small blood vessels and inappropriate platelet aggregation, leading to thrombocytopenia." (PMID 34281258, 2021). "Deficiency or dysfunction in ADAMTS-13 results in the life threatening microangiopathy termed thrombotic thrombocytopenic purpura (TTP)." (PMID 33571850, 2021). "Increased levels of ultralarge multimers resulting from deficiency of the metalloproteinase ADAMTS-13 are associated with the thrombotic disorder, thrombotic thrombocytopenic purpura." (PMID 33600794, 2021). "A severe deficiency of ADAMTS13 activity leads to thrombotic thrombocytopenic purpura (TTP), a specific thrombotic microangiopathy (TMA) characterized by neurologic and cardiac involvement." (PMID 34343182, 2021). "Thrombotic thrombocytopenic purpura (TTP) is a life-threatening thrombotic microangiopathy caused by severely reduced activity of the von-Willebrand factor-cleaving protease ADAMTS13, mainly caused by anti-ADAMTS-13 antibodies." (PMID 32219720, 2020).
thrombotic thrombocytopenic purpura (continued). "Thrombotic thrombocytopenic purpura (TTP) is a life-threatening hematological condition associated with deficiency in ADAMTS13." (PMID 33213410, 2020). "While ADAMTS13 mutations are well studied for heterogenous mutations across the gene in more than 200 congenital thrombotic thrombocytopenic purpura patients, only small numbers of patients and mutations have been reported in the other seven genes." (PMID 32183147, 2020). "ADAMTS 13 activity level was within normal limits at 44% ruling out ADAMTS13 deficiency and thrombotic thrombocytopenic purpura (TTP)." (PMID 31516395, 2019). "Deficiency of ADAMTS13 caused by either genetic mutations or by inhibitory autoantibodies against ADAMTS13 leads to thrombotic thrombocytopenic purpura (TTP)." (PMID 30679946, 2019). "It is well-known that dysfunction of ADAMTS13 is associated with diverse diseases, such as thrombotic thrombocytopenic purpura, pre-eclampsia, acute myocardial infarction, and diabetes." (PMID 31379722, 2019). "Thrombotic thrombocytopenic purpura (TTP) is a coagulation disorder caused by a deficiency in ADAMTS13." (PMID 31516768, 2019). "Complete deficiency in ADAMTS‐13 is the cause of thrombotic thrombocytopenic purpura (TTP), a thrombotic microangiopathy (TMA) whose hallmark symptoms are platelet‐ and VWF‐rich microvascular thrombi." (PMID 31294335, 2019). "Thrombotic thrombocytopenic purpura (TTP) is primarily caused by deficiency of ADAMTS13 within the blood stream due to either genetic defects or presence of inhibitory autoantibodies." (PMID 29777164, 2018). "Pregnancy, itself a procoagulant state, is a trigger for thrombotic thrombocytopenic purpura, especially in the setting of ADAMTS-13 deficiency." (PMID 30275392, 2018). "Thrombotic thrombocytopenic purpura has been related to the metalloprotease enzyme, ADAMTS13 deficiency." (PMID 30073173, 2018). "A deficiency of ADAMTS-13 is responsible for most cases of thrombotic thrombocytopenic purpura, generally occurring in the second and third trimester of pregnancy." (PMID 30275392, 2018). "Thrombotic thrombocytopenic purpura is a thrombotic microangiopathic disorder caused by a deficiency in the multidomain metalloprotease ADAMTS13 (A Disintegrin And Metalloprotease with ThromboSpondin type 1 repeats, number 13)." (PMID 28620373, 2017). "Deficient ADAMTS13 activity leads to thrombotic thrombocytopenic purpura (TTP), which is either congenital (due to mutations) or acquired (due to inhibitory antibodies)." (PMID 28139439, 2017). "Confirmation of thrombotic thrombocytopenic purpura (TTP) is increasingly reliant on demonstrating deficient ADAMTS‐13 activity." (PMID 26559391, 2016). "Accumulation of UL-VWF resulting from ADAMTS13 deficiency is characteristic of the microangiopathic disease thrombotic thrombocytopenic purpura (TTP), and has been reported in patients with both falciparum and vivax malaria." (PMID 25569250, 2015). "Approximately 40% of patients who survive acute episodes of thrombotic thrombocytopenic purpura (TTP) associated with severe acquired ADAMTS13 deficiency experience one or more relapses." (PMID 25671313, 2015). "Further testing revealed a deficiency of ADAMTS13 protein, or von Willebrand factor-cleaving protease, a finding diagnostic of congenital thrombotic thrombocytopenic purpura, or Upshaw-Schulman syndrome." (PMID 24288641, 2013). "A severe ADAMTS13 deficiency (activity <5%) either inherited or most often acquired via specific autoantibodies, is the main actor in the pathophysiology of thrombotic thrombocytopenic purpura (TTP)." (PMID 24238574, 2013). "Deficiency of ADAMTS13 as is present in patients with thrombotic thrombocytopenic purpura (TTP) results in the occurrence of microvascular platelet thrombi in different organs, demonstrating its physiological importance." (PMID 21909423, 2011).
thrombotic thrombocytopenic purpura (continued). "Mutations in the ADAMTS13 gene result in inappropriate platelet activation, leading to the blood disorder thrombotic thrombocytopenic purpura (TTP)." (PMID 15693998, 2005). "The development of autoantibodies targeting ADAMTS13 has also been reported in response to some therapies (e.g. ticlopidine, clopidogrel, immune checkpoint inhibitors) and is then referred to as drug-associated thrombotic thrombocytopenic purpura." (PMID 40372375, 2025). "An imbalance in the VWF/ADAMTS-13 axis has been implicated in the pathogenesis of thrombotic disorders, including thrombotic thrombocytopenic purpura (TTP), and may also be relevant in the context of PCS." (PMID 39941459, 2025). "ADAMTS13 (a disintegrin and metalloproteinase with a thrombospondin type 1 motif, member 13) is a metalloproteinase that cleaves the polymers of vWF, and diminished activity of ADAMTS13 is the diagnostic hallmark of thrombotic thrombocytopenic purpura." (PMID 39456810, 2024). "Normal ADAMTS13 activity suggests that thrombotic thrombocytopenic purpura is an unlikely cause of his anemia and thrombocytopenia, especially considering that he did not exhibit other associated symptoms such as fever, abdominal pain, and altered mental status." (PMID 39211639, 2024). "Congenital thrombotic thrombocytopenic purpura (cTTP) is an extremely rare disease characterized by the severe deficiency of a disintegrin and metalloproteinase with thrombospondin type 1 motifs 13 (ADAMTS13), caused by ADAMTS13 mutations." (PMID 37240470, 2023). "Thrombotic thrombocytopenic purpura is characterized by ADAMTS-13 deficiency, resulting in a deficient excision of the ultra-large VWF multimers presented in the VWF molecule on ECs, causing platelet adhesion and aggregation with rapid generation of disseminated microthrombi." (PMID 38034541, 2023). "Deficiency of ADAMTS13 leads to acquired thrombotic thrombocytopenic purpura (TTP)." (PMID 37954596, 2023). "Thrombotic thrombocytopenic purpura (TTP) is caused by a hereditary (cTTP) or immune-mediated (iTTP) deficiency of the enzyme ADAMTS13 (a disintegrin and metalloproteinase with a thrombospondin type 1 motif, member 13) and is one of the best characterized TMAs." (PMID 37176552, 2023). "Thrombotic thrombocytopenic purpura (TTP) is a thrombotic microangiopathy (TMA) caused by severely reduced ADAMTS13 or the von Willebrand factor-cleaving protease (VWFCP) enzyme resulting in low platelet and red blood cell counts along with severe renal, cardiac, and neurological dysfunction." (PMID 35494991, 2022). "However, abnormal accumulations of vWF caused by deficiency of plasma ADAMTS13 trigger intravascular platelet aggregation and micro thrombosis leading to a vascular disease, thrombotic thrombocytopenic purpura (TTP)." (PMID 34868193, 2021). "As a consensus of the International Working Group for Thrombotic Thrombocytopenic Purpura in 2017, thrombotic thrombocytopenic purpura can be distinguished from other causes of thrombotic microangiopathies by the finding of severe ADAMTS13 deficiency to less than 10%7." (PMID 34819564, 2021). "Thrombotic thrombocytopenic purpura is a very rare hereditary blood deficiency disorder of ADAMTS13 (von Willebrand factor-cleaving protease) and a life-threatening thrombotic microangiopathy characterized by thrombocytopenia and microangiopathic hemolytic anemia." (PMID 29357939, 2018). "Adamts13 encodes a large circulating protease responsible for processing multimeric von Willebrand factor (vWF) in vivo; mutations in human ADAMTS13 cause thrombotic thrombocytopenic purpura and variations in ADAMTS13 activity are associated with other thrombotic abnormalities." (PMID 25835743, 2015).